SNORD17 (small nucleolar RNA, C/D box 17)
Synonyms: HBI-43
Gene: Small nucleolar RNA gene on chromosome 20 (17,962,710 to 17,962,946, reverse strand). Ensembl gene ENSG00000212232.
Gene Ontology:
Biological process: RNA processing
Cellular component: nucleolus
Homologues: Orthologues: chimpanzee SNORD17 (99% identical), macaque SNORD17 (98% identical), dog SNORD17 (89% identical), pig SNORD17 (87% identical), rat Snord17 (86% identical), mouse Snord17 (86% identical).
Diseases named in the same sentence as SNORD17 in open-access papers:
SNORD17 is named in the same sentence as 7 diseases in open-access papers, as found by Europe PMC text mining. Sharing a sentence is not in itself a finding about the gene and the disease. The quoted sentences say what the papers report.
hepatocellular carcinoma (4 papers, 2022 to 2025). A malignant tumor that arises from hepatocytes. "Noncoding small nucleolar RNA SNORD17 is also related to carcinogenesis, including hepatocellular carcinoma, cervical cancer, and colon adenocarcinoma." (PMID 36274151, 2022).
colorectal cancer (1 paper, 2025). A primary or metastatic malignant neoplasm that affects the colon or rectum. "The Rn7sk, Rpph1, Rn7sl1, Rn7sl2, Znf460, Snord17, Snora73b, H1-4, H4c12, and H3c7 genes were discovered to be highly upregulated in the tumor tissue collected from colorectal cancer patients." (PMID 40427657, 2025).
liver cancer (1 paper, 2025). An epithelial or non-epithelial malignant neoplasm that arises from the liver.
SNORD17 also shares sentences with these, for which no sentence is quoted: cancer (3 papers); cervical cancer (1); colon adenocarcinoma (1); tumor (1).